CCR2 (C-C motif chemokine receptor 2)
Diseases named in the same sentence as CCR2 in open-access papers (continued):
Sharing a sentence is not in itself a finding about the gene and the disease.
liver disease (10 papers, 2012 to 2025). "Current researches have demonstrated that TNF, IL-1α/β, IL-1Ra, IL-6, IL-18, IL-33, IL-36, IL38, CCL2 and CCR2 are closely associated with liver disorders." (PMID 41333471, 2025). "In this review, we examined the reported evidence of the role of each CCR2 chemokine ligand in different stages of liver disease." (PMID 35281057, 2022). "In contrast, undifferentiated CD14+ monocytes can exacerbate liver disease, as shown by CCR2-mediated blockade of monocyte recruitment in models of liver disease." (PMID 28673774, 2017). "Relevant chemokine ligands of CCR2 in the pathogenesis of liver diseases." (PMID 35281057, 2022). "Since there is no comprehensive and up-to-date review of the functions of all known chemokine ligands of CCR2 in liver disease, the purpose of this article is to summarize all the information about the involvement of each chemokine ligand for CCR2 in the development of liver disease." (PMID 35281057, 2022). "Despite these possible confinements, intriguing data from murine steatohepatitis have given proof of the generic feasibility and efficacy of CCL2 antagonism by small molecules in combating liver diseases, Clinical trials involving CCR2 antagonists in non-liver disease entities are already at hand." (PMID 23091461, 2012). "Since CCL13 can bind to several chemokine receptors (CCR1, CCR2, CCR3, CCR5, or CCR11), it should have similar properties as other ligands of these receptors in the liver disease, but further studies are needed." (PMID 35281057, 2022). "Although a variety of chemokines have been well studied in various diseases, there is no comprehensive review presenting the roles of all known chemokine ligands of CCR2 (CCL2, CCL7, CCL8, CCL12, CCL13, CCL16, and PSMP) in liver disease, and this review aims to fill this gap." (PMID 35281057, 2022). "Cenicriviroc (CVC; a dual CCR2/CCR5 inhibitor) efficiently blocks CCL2 mediated monocyte recruitment and has been shown to exert anti-inflammatory and anti-fibrotic effects in various experimental liver disease models." (PMID 33868313, 2021). "The CCL2/CCR2, CCL5/CCR5 and CCL1/CCR8 are very common chemoattractant axes in liver diseases." (PMID 33868313, 2021). "In conclusion, dual CCR2/CCR5 inhibition primarily translates into reduced monocyte recruitment in acute liver injury in vivo, suggesting that this strategy will be effective in reducing inflammatory macrophages in conditions of liver disease." (PMID 28910354, 2017). "However, other ligands of CCR2 have not been thoroughly studied in liver diseases, especially CCL7, CCL8, CCL12, CCL13, CCL16, and PSMP." (PMID 35281057, 2022). "However, the specific functions of various CCR2 chemokine ligands in liver diseases are not entirely consistent." (PMID 35281057, 2022). "Therefore, targeting chemokine receptor CCR2 and its ligands for treating chronic liver disease and HCC has excellent prospects, especially in combination with immunotherapy, and further studies in preclinical animal models and liver disease patients’ clinical data are required." (PMID 35281057, 2022).
osteoporosis (10 papers, 2019 to 2025). A condition of reduced bone mass, with decreased cortical thickness and a decrease in the number and size of the trabeculae of cancellous bone (but normal chemical composition), resulting in increased fracture incidence. "The OR of CCR2 on CD62L+ plasmacytoid DC (cDC panel) risk on Osteoporosis was estimated to be 0.9993 (95% CI = 0.9987~0.9999, P = 0.035)." (PMID 39086903, 2024). "The OR of CCR2 on CD62L+ myeloid DC (cDC panel) risk on Osteoporosis was estimated to be 0.9992 (95% CI = 0.9984~0.9999, P = 0.048)." (PMID 39086903, 2024). "Human studies correlating Ccr2 and Ccl2 gene variants with osteopenia and osteoporosis risk demonstrated the important role of the CCR2 pathway in the skeletal system." (PMID 37371471, 2023). "In human studies, CCL2 and CCR2 gene variants were identified as potential risk factors for osteoporosis and osteopenia." (PMID 37457301, 2023). "According to MR findings from the current study, CCR2 activity on both plasmacytoid and conventional dendritic cells acts as a defensive mechanism against osteoporosis, aligning with the prevailing body of evidence." (PMID 39086903, 2024). "Genetic variants of CCR2 and MCP-1, a ligand for CCR2, have been suggested to correlate with osteoporosis." (PMID 39576015, 2024). "Mice deficient for Ccr2 were resistant to bone loss after OVX, suggesting a role for CCR2 signaling in estrogen-deficiency mediated osteoporosis." (PMID 31572390, 2019). "The significance of CCL2/CCR2 signaling in osteoclast function is mirrored by its contribution to diseases of the bone, such as RA, osteoporosis, multiple myeloma, tooth eruption, and bone metastasis." (PMID 31921102, 2019). "Last but not the least, CCR2 knockout mice were protected from osteoporosis caused by estrogen deficiency in a murine ovarectomy model compared to the wild-type ovarectomy group." (PMID 31921102, 2019). "In our study, CD11c on CD62L+ myeloid DC, CCR2 on CD62L+ myeloid DC, and CCR2 on CD62L+ plasmacytoid DC were all observed to be protective factors against osteoporosis." (PMID 39086903, 2024).
peripheral nerve injury (10 papers, 2017 to 2025). Injury to a peripheral nerve. "We took advantage of the transgenic reporter mice Cx3cr1GFP/+/Ccr2RFP/+ to trace tissue-resident macrophages (CX3CR1+) and monocytes recruited from the blood to inflamed tissue (CCR2+) after peripheral nerve injury." (PMID 37254842, 2023). "Consistent with that possibility, the chemokines CCL2, CCL3, and CX3CL1 are all highly expressed after peripheral nerve injury with the corresponding chemokine receptors, CCR2, CCR5, and CX3CR1 expressed by NK cells." (PMID 30712871, 2019). "It has been shown that during neuropathic pain caused by peripheral nerve injury, MCP-1 and Ccr2 expression increases in the DRG." (PMID 31417109, 2019). "After SCI, Ccl3 were induced significantly in the dorsal horns 2 days after lesion and remained at high levels with significantly higher intensities, while, after peripheral nerve injury, Ccl3 and their receptors (CCR2 and CCR1/CCR5, resp)." (PMID 29164149, 2017). "CCL2/CCR2-mediated NMDAR activity in D1R- and D2R-containing neurons after peripheral nerve injury." (PMID 37860084, 2023).
Cirrhosis (9 papers, 2015 to 2024). A chronic disorder of the liver in which liver tissue becomes scarred and is partially replaced by regenerative nodules and fibrotic tissue resulting in loss of liver function. "The marker has diagnostic value with an increase in CCR2+ cells observed as fibrosis advances and CCR2+ MoMF infiltration throughout the parenchyma in end-stage cirrhosis." (PMID 33868313, 2021). "CCR2 participates in liver pathology, including acute liver injury, chronic hepatitis, fibrosis/cirrhosis, and tumor progression, by mediating the recruitment of immune cells to inflammation and tumor sites." (PMID 35281057, 2022). "The inhibition of CCR2+ monocyte recruitment shows potential to improve fibrosis in patients with NASH, but needs further evaluation for the potential of cirrhosis reversibility and its effect on cirrhosis due to other underlying liver diseases." (PMID 36926073, 2022). "In contrast to CCR2 and CCR4, CD62L, a selectin implicated in preferential recruitment of blood monocytes to sites of inflammation, was specifically increased on monocytes from patients with decompensated cirrhosis." (PMID 27309850, 2016).
Hyperglycemia (9 papers, 2014 to 2026). An increased concentration of glucose in the blood. "To investigate the role of Tregs in hyperglycemia-induced hepatic inflammation, we generated chimeric mice by reciprocal bone marrow transplantation using WT, CCR2 KO, and DEREG mice." (PMID 27464894, 2016). "In the current study, we revealed that CCR2 expression on Tregs was significantly increased in mice with STZ-induced hyperglycemia." (PMID 27464894, 2016). "HSCs but not hepatocytes or LSEC showed higher CCL2 expression (which is the ligand with the highest affinity for CCR2) in STZ-induced diabetic mice, suggesting the possible migration of CCR2+ Tregs into the hyperglycemia-induced inflamed liver." (PMID 27464894, 2016). "During the hyperglycemia-induced inflammatory process, Tregs are critical for immune homeostasis in the liver and CCR2 expression on Tregs is required for migration into the inflamed liver." (PMID 27464894, 2016). "The neutrophils from the CCR2 KO or DEREG chimeric mice with hyperglycemia showed enhanced expression of IL-1β and TNF-α compared with those from the control mice." (PMID 27464894, 2016). "CCR2-mediated migration of Tregs regulates hyperglycemia-induced hepatic inflammation." (PMID 27464894, 2016). "Moreover, TNF-α expression in the infiltrating hepatic monocytes was enhanced in the DEREG chimeric mice with hyperglycemia compared to the WT or CCR2 KO chimeric mice with hyperglycemia." (PMID 27464894, 2016). "Interestingly, the expression of CCR2 on Tregs was significantly increased in mice with STZ-induced hyperglycemia compared to the control mice." (PMID 27464894, 2016). "Since the amelioration of hyperglycemia could contribute to the recovery of the immunosuppressive properties of DCs during the PR phase, tolerogenic DCs expressing CCR2 could be more active in the target tissue, diminishing in peripheral blood and prompting TREG responses." (PMID 35280980, 2022). "The regulatory impact of ERV1 on CCR2 and CX3CR1 in monocytes favored patrolling over inflammatory phenotype in both steady state and during dietary fat overload conditions, with a net positive metabolic impact reflected by prevention of hyperglycemia." (PMID 28993702, 2017). "Taken together, it is possible that the hyperglycemia and lack of improvement in IR noted with CCR2-/- may be related to direct enhancement of gluconeogenesis and persistent activation of alternate inflammatory circuits in the liver." (PMID 28253935, 2017).
inflammatory bowel disease (9 papers, 2018 to 2025). A spectrum of small and large bowel inflammatory diseases of unknown etiology. "It was reported that CCR2+ monocytes promote colon fibrosis by inhibiting collagen degradation through tissue inhibitor of metalloproteinase (TIMP-1) production in inflammatory bowel disease (IBD)." (PMID 32626718, 2020). "A novel circulating pro-inflammatory monocyte subset, defined by double positive, CCR2+CX3CR1+ cells, was recently described in patients with inflammatory bowel disease." (PMID 41254741, 2025). "Furthermore, anti-TNF non-responders with inflammatory bowel disease had upregulated CCR2 expression, which might cause lower serum CCL2 levels than those seen in the responders." (PMID 34367126, 2021). "In contrast to inflammatory bowel disease (IBD) or infectious diseases of the gut, the inflammatory milieu instigated by DEP is not a consequence of increased CCR2+ pro-inflammatory macrophages, but decreased CCR2− anti-inflammatory/resident macrophages." (PMID 37400850, 2023).
liver cancer (9 papers, 2020 to 2025). An epithelial or non-epithelial malignant neoplasm that arises from the liver. "Blocking CCL2/CCR2 signaling pathway can block the recruitment of monocytes and M2 polarization of tumour-associated macrophages (TAMs) in liver cancer." (PMID 39816386, 2024). "The association between the expression of genes in the CCL2/CCR2 and CXCL8/CXCR2 axes and patient OS in the TCGA liver cancer dataset was analyzed." (PMID 36403057, 2022). "The study showed that after injecting CCR2 antagonist into the abdominal cavity of mice with in-situ liver cancer model, the number of TAMs in liver cancer tumour was significantly reduced, while CD8+ T cells were significantly increased, which significantly inhibited tumour growth." (PMID 39816386, 2024). "Through their interaction with specific receptors, such as CCR1, CCR2, CCR3, etc., these chemokines play a crucial role in the evolution of liver cancer." (PMID 40062588, 2025). "Lentiviral knockdown of CCL2 or the CCR2 inhibitor CCX872 significantly attenuated ETV4-induced invasion of TAMs and MDSCs and metastasis of liver cancer." (PMID 39816386, 2024). "To further confirm these results, we compared the expression levels of the CCL2/CCR2 and CXCL8/CXCR2 genes in HCC tumors and adjacent normal tissues using data from the TCGA liver cancer database." (PMID 36403057, 2022). "Here, we evaluated the feasibility of targeting CCR2 and CXCR2 with their respective antagonists INCB3344 and SCH527123 for liver cancer therapy." (PMID 36403057, 2022). "In our CCR2/CCR4 double-K/O model, Foxp3+ Treg infiltration was reduced, while a meaningful infiltration of CD8+ T cells was observed in our CCR2/CCR4 double-K/O model, similar to what was obtained in a model of liver cancer following CCR2 K/O or neutralization." (PMID 35980743, 2022). "The results showed that CCL2, CCR2, CXCL8, and CXCR2 were more highly expressed in adjacent normal tissues than in liver cancer tissues." (PMID 36403057, 2022).
metastatic tumors (9 papers, 2011 to 2022). "Patients with high expression of TRAIL-R3 and CCR-2 in TEpCs were at significantly higher risk for metastatic tumors than patients with low expression." (PMID 28420351, 2017). "Indeed, in a grafted tumor model, CCR2 inhibition was effective at reducing TAMs, which is consistent with our finding here in autochthonous primary and metastatic disease that TAM reductions render PDA susceptible to ICB." (PMID 36256464, 2022). "Taken together, these data suggest that the depletion of CCR2-mediated macrophage infiltration profoundly decreases metastatic disease." (PMID 36256464, 2022). "Our data revealed the highly upregulated expression of CCR2 in metastatic tumors compared to benign and malignant tumors as well as healthy tissue." (PMID 32225066, 2020). "Certain patients with metastatic (5/11) or non-metastatic tumors (2/42) expressed high levels of CCR-2." (PMID 28420351, 2017). "Experimental evidence from various pre-clinical cancer models have been encouraging and indicate that CCL2 and CCR2 are attractive targets for intervention of metastatic diseases." (PMID 26885690, 2016). "Furthermore, our data demonstrated that CX3CR1 deficiency suppressed macrophage expression receptors CCR2, VEGFR2, and CXCR4 (cell surface markers of angiogenic macrophages) in hepatic metastatic tumors." (PMID 24245985, 2013). "We further evaluate the outcome of several clinical trials targeting either CCL2 or CCR2, and discuss the prospects and challenges of manipulating CCL2-CCR2 interaction as a potential approach for combating metastatic disease." (PMID 26885690, 2016). "Specifically, CXCR6, CCR2, CCR4, IL2Ra were both deleted and had lower gene expression in the primary versus metastatic tumors." (PMID 22194851, 2011). "Interestingly, metastatic tumors exhibit increased expression of CXCR3, CCR2, IL-4, IL-12p40, and IL-17." (PMID 32225066, 2020). "Despite these encouraging results, a treatment with single chemokine antagonist will not be enough to suppress metastatic tumor growth since even total deletion of CCR1, CCR2, or CCR5 by knockout cannot achieve complete elimination of metastatic tumors in mouse models." (PMID 30483271, 2018). "In these models, blockade of MAM accumulation via genetic deletion of CCR1, CCR2 or CCR5 significantly reduced metastatic tumor burden, suggesting that antagonists for these receptors can be novel therapeutic agents to prevent metastatic tumor development through inhibition of MAM accumulation." (PMID 30483271, 2018).
neuropathy (9 papers, 2010 to 2022). A disorder affecting the nervous system that manifests with pain, tingling, numbness, and/or muscle weakness. "Some studies have suggested that both resident and infiltrating spinal microglia activated by CCR2 contributed to enhanced neuronal excitation during the development of nerve injury induced neuropathy." (PMID 21143971, 2010). "The CCR2/CCL2 system has been identified as a regulator in the pathogenesis of neuropathy-induced pain." (PMID 21143971, 2010). "Curiously, CCR2 knockout mice developed similar initial neuropathy to that in control littermates, whilst during the second cycle CCR2-deficient mice had less mechanical neuropathy than controls, and also presented less expression of the macrophage marker than the controls." (PMID 35418856, 2022). "The most recent studies have highlighted the importance of CCR2 and CCR5 in pathological nociceptive transmission under neuropathy." (PMID 33408720, 2020).
nonalcoholic steatohepatitis (9 papers, 2019 to 2024). "Furthermore, a recent study reported that cenicriviroc (CVC), a dual CCR2 and CCR5 antagonist, was used in a phase IIb clinical trial involving 289 adult patients with nonalcoholic steatohepatitis (NASH) and fibrosis." (PMID 39632841, 2024). "In addition, both preclinical and clinical studies have shown that a dual CCR2/CCR5 antagonist, cenicriviroc (CVC), is an effective and safe antifibrotic agent for treating nonalcoholic steatohepatitis (NASH) and alcohol-induced steatohepatitis." (PMID 35281057, 2022). "Recent reports from phase 2 clinical trials in patients with non-alcoholic steatohepatitis (NASH) showed reduced liver fibrosis when targeting macrophages using the inhibitor of the serine/threonine kinase ASK1, selonsertib, or the dual CCR2/CCR5 inhibitor cenicriviroc." (PMID 33802948, 2021).